GSTM2 (glutathione S-transferase mu 2)
Diseases named in the same sentence as GSTM2 in open-access papers (continued):
Sharing a sentence is not in itself a finding about the gene and the disease.
cancer (28 papers, 2007 to 2025). A tumor composed of atypical neoplastic, often pleomorphic cells that invade other tissues. "The epigenetic regulation of GSTM2 has been associated with several cancers, among which is PCa, although there are far less studies compared to GSTP1, and far more variable findings in the context of proteomics PCa studies." (PMID 36553191, 2022). "Genes reported upregulated by Tris DBA palladium in vivo include GSTM2, which has been associated with improved prognosis in solid tumors and often demonstrates promoter hypermethylation in advanced cancer." (PMID 31320995, 2019). "In High 2 or Basal groups, downregulation of GSTA1, GSTM1, GSTM2, and GSTT1 gene expression can be correlated with the impaired ability to eliminate carcinogenic compounds and increased cancer risk." (PMID 40426890, 2025). "We then investigated the association of GSTP1 and GSTM2 promoter methylation with the TMB and CNA burdens and expression of the proliferation marker Ki-67 in all other cancer types from TCGA." (PMID 34871444, 2021). "GSTM2 prevented programmed cell death of cancer cells through autophagy inhibition and lysosome dysfunction in an aminochrome-treated GBM cell line." (PMID 34209254, 2021). "The result of analysis of the GST family and cancer shows significant ORs of GSTM1 and GSTM2 on cancer [1.110 (95% CI: 1.080–1.141) and 1.125 (95% CI: 1.073–1.180), respectively]." (PMID 27045371, 2016). "Taken together, these results imply that there is an association between cancer progression and GSTM1 gene copy number, which is in general agreement with our observation that the expression of other genes from GST family (GSTM2 and GSTT1) is also copy number dependent." (PMID 39726707, 2024). "Both GSTM1 and GSTM2 play important roles in cell detoxification, protecting cells against cancer." (PMID 35008958, 2022). "In addition, predictive function of low GSTM2 and GSTM1 were involved in the cell cycle, which is associated with the occurrence of cancers and outcome." (PMID 32539715, 2020). "Eighteen overlapping DEGs were identified between the two CRC cell lines, four of which are closely related to cancer progression, namely FGF1, THBS2, DAPK2, and GSTM2." (PMID 41039172, 2025). "We further verified the expressions of the oxidative stress-responsive genes and the cholesterol biosynthesis-related genes using qPCR in the GBM cancer cells and recorded an increase in the mRNA levels of HMGCR, HMCGS1, DHCR24, GSR, GSTM2 and GCLC after MPT0L145 treatment in U87MG and M059K cells." (PMID 34885226, 2021). "There are no further reports about the relationship between the GSTM2 and cancer prognosis." (PMID 32539715, 2020).
tumor (23 papers, 2006 to 2025). "Although our study focuses on GSTM5, it is part of the larger GST family, which includes GSTM1 and GSTM2, both of which have been implicated in tumor progression and treatment response." (PMID 40868127, 2025). "The results showed that GSTM2 expression was associated with the activities of signatures including cellular response to hypoxia, tumor proliferation signature, apoptosis, DNA repair, G2M checkpoint, MYC targets, TGFB, DNA replication, and degradation of ECM." (PMID 36263204, 2022). "Furthermore, relative mRNA expression of GSTM2 was significantly decreased among tumors with high array methylation at both CpGs associated with tumor grade (P<0.001 and P<0.03)." (PMID 20686660, 2010). "Additionally, our study revealed a negative correlation between GSTM2 expression and γδ T cell infiltration, suggesting that GSTM2 deficiency may lead to excessive accumulation of γδ T cells in the tumor microenvironment, which is consistent with previous reports." (PMID 40508038, 2025). "Two of the 16 dmCpGs were in genes that were significantly down-regulated in Australian tumour samples (Bonferroni p < 0.01; GSTM2 and PRKCB)." (PMID 39095452, 2024). "Of our 16 LASSO-selected dmCpGs, two were present in genes, PRKCB and GSTM2, that were significantly down-regulated in tumour compared with benign samples (Bonferroni p-value < 0.01)." (PMID 39095452, 2024). "The results of previous studies showed that GSTM2 mRNA levels were significantly lower in the tumor tissues of NSCLC patients compared to the paired adjacent normal tissues." (PMID 38111060, 2023). "When we analyzed the GSTM2 expression in tumor cells, we found that the patients with lower GSTM2 immunohistochemical scores frequently had poorer OS (p = 0.12, HR = 1.487, 95%CI (0.9877 - 2.4707)." (PMID 36263204, 2022). "As a result, the expression of GSTM2 protein was significantly lower in cancerous tissues compared to their paired non-tumor tissues." (PMID 36263204, 2022). "GSTM2 co-expressed genes were not only involved in tumor-related pathways, but also in immune-related pathways, such as chemokine signaling pathway and cytokine binding." (PMID 36263204, 2022). "To establish a direct link between GSTM1 and GSTM2 activity and tumor growth rate, we tested if their promoter methylation status is associated with the expression of the marker of proliferation Ki-67." (PMID 34871444, 2021). "Regarding clinical data, tumor stage provided the highest contribution risk score, and high expression of GSTM1 and GSTM2 showed higher contribution risk scores for COAD patients." (PMID 32539715, 2020). "Higher methylation at one or more CpG sites in the upstream regulatory region of GSTM2 was correlated with increasing stage, larger tumor size, and higher grade." (PMID 25287138, 2014). "A promoter CpG in GSTM2 had significantly increased methylation with increasing tumor grade and array methylation was significantly correlated with Sequenom methylation (rho = 0.83, P<2.2E-16, n = 140)." (PMID 20686660, 2010). "With respect to tumour grade, we identified only one gene (GSTM2) that was significantly different among 10 genes that were present in both data sets." (PMID 16969345, 2006). "Hypermethylation of the glutathione S-transferase mu 2 (GSTM2) promoter has been identified as a potential biomarker for aggressive tumor behavior and may contribute to the progression of estrogen receptor (ER)-and progesterone receptor (PR)-negative BRCA." (PMID 41278297, 2025). "GSTM2 is known to play a tumor suppressor role, and functional characteristics that may also be shared GSTM5; therefore, the effects of GSTM1-5 on cell viability were compared by overexpressing these proteins in 5637 cells." (PMID 33802702, 2021). "Low expression of GSTM1 and GSTM2 was related to favorable OS (adjusted P = 0.006, adjusted HR = 0.559, 95% CI = 0.367–0.849 and adjusted P = 0.002, adjusted HR = 0.519, 95% CI = 0.342–0.790, respectively) after adjusting for tumor stage." (PMID 32539715, 2020).
tumor (continued). "Moreover, studies have shown that GSTM2 regulates tumor cell metastasis and treatment sensitivity." (PMID 38825668, 2024). "At the same time, we also evaluated the effects of GSTM2 protein expression on patient survival after grouping the patients into two groups based on the best cutoff value of GSTM2 expression (the best cutoff value of GSTM2 expression in tumor cell group was 1, and in lymphocyte group was 0.075)." (PMID 36263204, 2022). "Additionally, in all cases, Sequenom methylation values were significantly associated with respective covariates; tumor stage with FES methylation (P = 0.05), tumor size with P2RX7 (P<0.005) and HSD17B12 methylation (P<0.02), and tumor grade with GSTM2 methylation (P<0.001)." (PMID 20686660, 2010). "Therefore, the patients with low GSTM2 expression might have low infiltrating ratios of T cell CD8+, thereby the tumor initiation may be promoted." (PMID 36263204, 2022).
infection (11 papers, 2008 to 2023). The state of being infected such as from the introduction of a foreign agent such as serum, vaccine, antigenic substance or organism. "However, overexpression of GSTM2 by AAV9-GSTM2 infection notably alleviated DNA damage, as evidenced by decreased γ-H2AX expression in PE-treated cardiomyocytes and inhibiting of 8-OHDG production and eccDNA release in mouse HF samples." (PMID 38037116, 2023).
GSTM2 also shares sentences with these, for which no sentence is quoted: Alzheimer disease (2 papers); Barrett adenocarcinoma (2); neuropathy (2); ovarian teratoma (2); schizophrenia (2); -amyloid (1); abortion (1); anemia (1); Arrhythmia (1); Arthritis (1); astrocytomas (1); bronchopulmonary dysplasia (1); cataract (1); cervical cancer (1); coronary heart disease (1); gastrointestinal disease (1); gout (1); heart failure (1); hyperlipidemia (1); idiopathic dilated cardiomyopathy (1); Insulin resistance (1); lupus nephritis (1); Machado-Joseph disease (1); melanoma (1); Meningeal tumors (1); myocardial infarction (1); nephritis (1); neurodegenerative disease (1); neurotoxicity (1); oral squamous cell carcinoma (1).
A further 8 diseases each share a sentence with GSTM2 in 1 paper.